BRAF (B-Raf proto-oncogene, serine/threonine kinase)
Diseases named in the same sentence as BRAF in open-access papers (continued):
Sharing a sentence is not in itself a finding about the gene and the disease.
colorectal cancer (continued). "According to the guideline by the American Society for Clinical Pathology, College of American Pathologists, Association for Molecular Pathology, and American Society of Clinical Oncology on biomarker evaluation in colorectal carcinoma, evaluation of mutation in BRAF and KRAS genes is recommended." (PMID 39364024, 2024). "While HES1 expression is normal in benign hyperplastic polyps and normal colon tissue, HES1 expression is often lost in sessile serrated adenomas/polyps (SSAs/SSPs) and colorectal cancers (CRCs) such as those right-sided CRCs that commonly harbor BRAF or KRAS mutations." (PMID 36824959, 2023). "In terms of further study on the topic, a mention should be made of the evidence for which 10% of colorectal cancer patients carry BRAF V600E and BRAF-related mutations, whose event is associated with a worse prognosis and poor outcomes towards systemic therapies." (PMID 36672435, 2023). "Notably, CIMP colorectal cancer is associated with BRAF V600E and KRAS mutations, CDX2 loss, as well as low chromosomal aberrations and high microsatellite instability (MSI), which is reported to be driven by methylation of hMLH1 gene." (PMID 37234978, 2023). "The role of BRAF p.N581I mutation in colorectal cancer demands more attention." (PMID 37519790, 2023). "In addition, the UPR was previously identified as a pathway significantly associated with the BRAF-mutated colorectal cancer subgroup with poor prognosis." (PMID 37106808, 2023). "Patients with BRAFV600E-mutated colorectal cancer have encouraging overall response rates to inhibition of PD-1, BRAF and MEK, with translational analyses suggesting that induction of tumor-intrinsic programs and immune programs contributes to improved outcomes via MAPK inhibition." (PMID 36702949, 2023). "KRAS or rapidly accelerated fibrosarcoma isoform B (BRAF) mutations that occur in colorectal cancer may also contribute to glucose uptake and GLUT1 overexpression." (PMID 37107291, 2023). "This EPPV study provides safety information for a 6-month period after the administration of encorafenib and binimetinib in Japanese patients with advanced BRAF V600E-mutated colorectal cancer, which is the first real-world safety data of the triplet and doublet regimens for colorectal cancer." (PMID 36355316, 2023). "We hypothesized that different KRAS/BRAF mutational statuses of colorectal cancer cell lines affect the effectiveness of HAMLET anticancer and mitochondrial activity." (PMID 37099199, 2023). "The doublet regimen has been approved for unresectable advanced or recurrent colorectal cancer with the BRAF V600E mutation in the United States, the European Union, Japan, and Korea, while the triplet regimen has been approved for the same indication only in Japan." (PMID 36355316, 2023). "The activating mutations in BRAF oncogene are found in approximately 10% of colorectal cancers." (PMID 37151068, 2023). "Overall, our work unveils the long-term impact of BrafV600E expression in intestinal tissue and suggests that colorectal cancers with mutations in BRAF might be prevented by statins." (PMID 37735514, 2023). "Among the frequently mutated colorectal cancer-associated genes, only BRAF mutations showed a higher prevalence in the older patient group (23.9% versus 9.9% in younger patients, Fisher’s exact test p = 0.002), while other genes had similar mutation rates in the two groups." (PMID 37763693, 2023). "The BRAF mutation in colorectal cancer (CRC) is associated with a poor prognosis." (PMID 38201408, 2023). "Thus, this study aimed to generate real-world evidence to supplement the growing body of research surrounding BRAF mutations in the clinical management of colorectal cancer." (PMID 38136294, 2023). "Although genetic alterations and tumorigenesis processes remain unclear, mucinous differentiation of colorectal cancers are associated with high frequency of mutations in KRAS or BRAF." (PMID 37496011, 2023).
colorectal cancer (continued). "Encorafenib is approved in the United States and elsewhere in combination with binimetinib to treat BRAF V600E or V600K mutation‐positive unresectable or metastatic melanoma or in combination with cetuximab to treat BRAF V600E mutation‐positive colorectal cancer." (PMID 37775918, 2023). "BRAF mutations are predominantly present in the CMS1 subtype of colorectal cancers." (PMID 37998722, 2023). "BRAF mutant colorectal cancer patients with high microsatellite instability/DNA deficient mismatch repair (MSI-H/dMMR) have high tumor mutation burden and abundant neoantigen, who are deemed as ones that could receive expected efficacy from immunotherapy." (PMID 37302081, 2023). "Colorectal cancer (CRC) patients with BRAF mutation have very poor prognosis." (PMID 37409251, 2023). "In total, 81 colorectal cancer patients with BRAF mutations were identified in our data base." (PMID 37466791, 2023). "Therefore, in the medical care for colorectal cancer, if the dMMR testing result shows MSI-H or the loss of MLH1/PMS2 expression, checking for the BRAF V600E mutation helps distinguish Lynch syndrome-related colorectal cancers from sporadic ones." (PMID 37599324, 2023). "BRAF inhibition introduced by V600E mutation causes a rapid feedback activation of human epidermal growth factor receptor (HER)/epidermal growth factor receptor (EGFR) in colorectal cancer cell lines." (PMID 36624452, 2023). "BRAF non-V600 mutation occupies a relatively small but critical subset in colorectal cancer (CRC)." (PMID 37853469, 2023). "Oncogenic mutations in BRAF genes are found in approximately 5–10% of colorectal cancers." (PMID 36856908, 2023). "Regarding BRAF mutations, 56% (14/25) of colorectal cancer with BRAF V660E mutation (BRAFV600E-CRC) were infected with Fn whereas significantly fewer of the colorectal cancers with wild-type BRAF (non-BRAFV600E-CRC; 34%: 95/279) were infected with Fn (OR: 2.39, P = 0.04)." (PMID 37772997, 2023). "Besides BRAF mutations, BRAF inhibitor sensitivity in colorectal cancer cell lines is conferred by SACS mutations and PRKN locus loss." (PMID 36295658, 2022). "Despite the key function of PI3K/AKT/mTOR activity in a sub-set of BRAF mutated colorectal cancers, few trials have attempted to target the pathway in these cancers or to systematically exploit therapeutically the sub-set with concomitant BRAF and PIK3CA mutations." (PMID 36079062, 2022). "Of note, it has been reported that ERK5 is dispensable for proliferation of colorectal cancer cells carrying KRAS/BRAF mutations, suggesting that genetic mutational background must be considered to establish the exact role of ERK5 in proliferation of different cancer types." (PMID 36123565, 2022). "A subsequent study showed that radiomics texture features could serve as potential biomarkers for determining BRAF mutation status and as predictors of 5-year prognostic outcome in patients with advanced-stage colorectal cancer." (PMID 36060960, 2022). "Indeed, activation of the WNT/β-catenin pathway is required even in the presence of SMAD4 inactivation in BRAF-associated colorectal cancers." (PMID 36079062, 2022). "Besides, 46 PDX tissues of colorectal cancer were detected with the mutation status of RAS/BRAF genes, including 24 patients with RAS mutation and five patients with BRAF mutation." (PMID 36465411, 2022). "Moreover, high miR-31 expression is significantly associated with BRAF mutations in colorectal cancers." (PMID 35566730, 2022). "BRAF gene abnormalities in small intestinal adenocarcinoma occur in a little less than 10% of cases, but V600E mutations account for under 1%, which is different than in colorectal cancer." (PMID 35566730, 2022). "Given that the prevalence of APC mutations is shown to be lower in BRAF mutated colorectal cancers, alternative modes of pathway activation are at play and may involve inhibition of kinase GSK3 through PI3K/AKT signaling." (PMID 36079062, 2022).
colorectal cancer (continued). "In addition to ATM, other genes related to DNA damage response (DDR) are mutated in smaller percentages of colorectal cancers and show a predilection for BRAF mutated cancers." (PMID 36079062, 2022). "Moreover, MSS tumours with BRAF mutations usually have high methylation levels, suggesting that the poor survival of patients with colorectal cancer with BRAF mutations is attributed to the relationship between high methylation levels and poor prognosis." (PMID 35359593, 2022). "Additionally, we compared and contrasted SAMHD1 expression according to KRAS mutation status, BRAF mutation status, tumor location, and defective DNA mismatch repair status, as they were frequently mutated genes or risk parameters in colorectal cancer." (PMID 35978833, 2022). "KRAS mutations are more common than BRAF mutations and are present in 30–40% of colorectal cancers." (PMID 36079062, 2022). "The RAS and BRAF mutation statuses of 253 formalin-fixed paraffin-embedded (FFPE) colorectal cancer tissues were analyzed using the Investigational Use Only IdyllaTMKRAS Mutation Test and the IdyllaTMNRAS-BRAF Mutation Test and an in vitro diagnostics (IVD) kit (MEBGEN RASKETTM-B kit)." (PMID 35474548, 2022). "In colorectal cancers, the prevalence of BRAF mutations is 8–12%." (PMID 36079062, 2022). "However, increased SPINK1 secretion was reported to be related to vemurafenib resistance in BRAF V600E-mutant colorectal cancers, indicating the need to target different gene variant subtypes of HCC during chemotherapy (29193645)." (PMID 36246599, 2022). "Besides, in patients with colorectal cancer, BRAF-mutated disease has been associated with generally decreased HRQL." (PMID 36116420, 2022). "Oncogene KRAS mutations are rather rare in BRAF mutant colorectal cancers, occurring in 10% of such cancers in TCGA and in about 5% in the DFCI cohort, compared with 37.8% and 31.6% in cancers with BRAF and PIK3CA wild type and 64.8% and 43.3% of cancers with BRAF wild type and PIK3CA mutations." (PMID 36079062, 2022). "This investigation examines colorectal cancer cell lines bearing BRAF mutations with concomitant PIK3CA mutations and compares them to BRAF mutant cell lines without PIK3CA mutations in regard to genomic characteristics such as ploidy, MSI status, and coexisting molecular alterations." (PMID 36295658, 2022). "About 60% of sporadic MSI high colorectal cancers exhibit BRAF mutations." (PMID 36079062, 2022). "However, the presence of PIK3CA mutations in BRAF mutated colorectal cancers leads to a numeric increase in the prevalence of MSI (from 59.5% to 68.2% in TCGA and from 47.1% to 62.9% in the DFCI cohort)." (PMID 36079062, 2022). "Prediction of KRAS/NRAS/BRAF mutations in colorectal cancer (CRC)." (PMID 35740526, 2022). "Therefore, clinicopathological and molecular characteristics of colorectal carcinoma with KRAS/BRAF double mutations are unclear." (PMID 35280113, 2022). "Fn is implicated in the progression of advanced colorectal carcinoma and associated with clinical and molecular features, such as the proximal tumor location, BRAF mutation, MSI-high status, downregulating of antitumor T cell-mediated adaptive immunity, CRC staging, and a worse patient prognosis." (PMID 35054281, 2022). "We examined and analyzed mutation status of KRAS/NRAS/ BRAF in colorectal cancer tissues." (PMID 33816307, 2021). "Furthermore, it was reported that the autophagy regulators LC3 and Beclin1 are expressed at higher levels in BRAF-mutated colorectal cancer cell lines, and that pharmacological inhibition of BRAFV600E signaling resulted in reduced expression of these proteins." (PMID 34298710, 2021). "Therefore, for colorectal cancer patients with the BRAF V600E mutation, FOLFOXIRI combined with bevacizumab is more effective than other chemotherapy regimens." (PMID 34567559, 2021). "We supposed that there may be some correlation between BRAF mutation and rhabdoid features in colorectal cancers." (PMID 33903966, 2021).
colorectal cancer (continued). "For instance, in colorectal cancer with BRAF mutations, BRAF inhibitors alone are ineffective." (PMID 33427211, 2021). "The inhibition of PBK/TOPK could benefit those colorectal cancer patients with a KRAS or BRAF mutation and those with metastasis, which represented 30–40% of all cases, and this may represent a new avenue of investigation for targeted therapy." (PMID 33670114, 2021). "In clinical settings, PBK/TOPK expression is an unfavorable prognostic indicator in patients with sporadic colorectal cancer with mutations in the proto-oncogene KRAS or BRAF and in patients with metastatic disease experiencing a response to anti-EGFR monoclonal antibody therapies." (PMID 33670114, 2021). "KRAS, NRAS, and BRAF mutations are commonly present in colorectal cancer (CRC)." (PMID 33979337, 2021). "In addition, the TF-IDF value of BRAF mutation in colorectal cancers increased because of the better outcomes of the BRAF-mutant CRC tumors with microsatellite instability (MSI) in immunotherapy." (PMID 34759963, 2021). "The real-world performance of standard chemotherapy in metastatic BRAF variant colorectal cancer may be superior to that reported in the BEACON trial." (PMID 33433598, 2021). "However, colorectal cancer cell lines with KRAS/BRAF mutations exhibited increased GLUT1 expression, independent of HIF1α status in normoxic conditions." (PMID 33420213, 2021). "The overwhelming majority of mutation of BRAF was conducive to gain-of-function and plays a role of oncogene, with high frequency of V600 E variant, which had been uncovered as a treatment target in papillary thyroid cancer, lung cancer, and colorectal cancer." (PMID 33014052, 2020). "However, caution is needed, because it has been reported that the BRAF V600E mutation was detected in some colorectal cancers that developed in patients with Lynch syndrome attributable to the PMS2 gene." (PMID 31286289, 2020). "Notably, a multicenter study investigating the biomarkers of immune checkpoint inhibitor response in patients with MMR-D colorectal cancer identified BRAF V600 mutations and specific types of MMR genes as a predictor of worse 12- and 24-month PFS rates." (PMID 32670606, 2020). "The use of VPE in functional foods or nutraceuticals could be exploited in personalized anti colorectal cancer dietary strategies, because higher sensitization to the drug 5-FU is achieved in BRAF mutated tumors, relative to KRAS mutated tumors." (PMID 32806531, 2020). "The highest correlation coefficients were observed between NETO2 expression and pathological stage for breast cancer (rs = 0.15) and prostate cancer (rs = 0.25), tumor differentiation for prostate cancer (rs = −0.16), and BRAF mutation status (rs = 0.18) for colorectal cancer." (PMID 33362854, 2020). "Clinical characteristics of colorectal cancer patients with BRAF mutation." (PMID 33330032, 2020). "Its mRNA expression was also associated with k-ras and BRAF mutation in colorectal cancer." (PMID 33330092, 2020). "Multivariate analysis for patients with BRAF mutated colorectal cancer." (PMID 33330032, 2020). "Further, it has been known since recently that m-CRC with mutated RAS is resistant to anti-EGFR therapies, and those with MSI phenotype are sensitive to immunotherapy, but colorectal cancer with BRAF mutation/s is awaiting such a specific chemotherapeutic approach." (PMID 33738242, 2020). "Therefore, in the medical care for colorectal cancer, if the dMMR-testing result shows MSI-H or the loss of MLH1/PMS2 expression, checking for the BRAF V600E mutation helps distinguish Lynch-associated colorectal cancers from sporadic ones." (PMID 31286289, 2020). "Conclusions: the WNT signaling axis is frequently mutated in BRAF mutant colorectal cancers." (PMID 32384699, 2020). "It was positively correlated with K-ras mutation and BRAF mutation of colorectal cancer (P < 0.05)." (PMID 33330092, 2020). "The pathological diagnosis revealed BRAF mutated colorectal carcinoma." (PMID 32785802, 2020).
colorectal cancer (continued). "CIMP-H colorectal carcinomas have a distinct clinical, pathologic and molecular profile, including associations with female gender, proximal tumor location, mucinous-type and poor differentiation, dMMR and BRAF mutations." (PMID 32231042, 2020). "BRAF V600E mutation and drug resistance to BRAF inhibitors occurs also in colorectal cancer." (PMID 31877948, 2019). "KRAS, NRAS and BRAF mutations occur in colorectal cancers in a mutually exclusive manner." (PMID 31711486, 2019). "Literature reports also suggest a prognostic role for this BRAF mutation in colorectal cancer." (PMID 31352904, 2019). "Oncogenic mutations in KRAS or BRAF are frequent in colorectal cancer and activate the ERK kinase." (PMID 31266962, 2019). "Such inhibitors are now in clinical use and do also target oncogenic MEK mutations in colorectal cancers, which may occur secondarily to BRAF inhibitor treatment." (PMID 30899445, 2019). "Metastatic colorectal cancer with BRAF V600E mutation is rare but has a very poor prognosis." (PMID 30800219, 2019). "These speculations seem to be confirmed by recent discoveries obtained in murine models bearing the BRAF mutated colorectal cancer that proved that the persistent oncogenic BRAF signalling is sufficient to induce a progressive widespread DNA methylation." (PMID 31861757, 2019). "In addition to these, previously, BRAF Val600Glu mutation has been associated with the increased risk of mortality in colorectal cancer." (PMID 31352904, 2019). "BNA-clamp PCR accurately detected KRAS, NRAS and BRAF mutations in patients with colorectal cancer." (PMID 31711486, 2019). "Colorectal cancers that harbour the same BRAF(V600E) mutation are intrinsically resistant to BRAF inhibitors, due to feedback activation of the epidermal growth factor receptor (EGFR), although double or triple combination trials gave some benefit in terms of response rate." (PMID 31762942, 2019). "The BRAF gene encodes a cytoplasmic serine-threonine kinase that is frequently mutated in various cancers, including melanoma, papillary thyroid carcinoma, and colorectal carcinoma, among others." (PMID 29127628, 2019). "Characteristics of BRAF V600E mutation-positive cases in Thai colorectal cancer tissues." (PMID 29879227, 2018). "This indicates that in a proportion (4/45, 9%) of this particular BRAF mutant colorectal cancer subgroup, IDH1 mutation may contribute to CIMP." (PMID 30598662, 2018). "In this study, we systematically described and statistically analyzed the frequencies and distributions of KRAS/NRAS/BRAF genetic mutation status and their relationship with IHC in 260 cases with colorectal cancer or gastric cancer through retrospective analysis." (PMID 30416987, 2018). "Moreover, combining AZ304 and the anti-EGFR monoclonal antibody Cetuximab resulted in significantly improved anti-tumour activity in colorectal cancer cells both in vitro and in vivo, independently of BRAF mutation status." (PMID 29755114, 2018). "Further testing and larger study populations may ultimately confirm BRAF mutational status as an additional and much needed biomarker for colorectal cancer and ensure its inclusion in routine screening outside of clinical trial settings." (PMID 30598662, 2018). "BRAF mutation is found in around 80–90 % of sporadic MSI-H colorectal cancers." (PMID 29507659, 2018). "The susceptibility to higher levels of oxidative stress was also observed in other tumor types that harbored a mutation in BRAF, as mutant BRAF colorectal cancer cells are prone to cell death after exposure to the oxidized form of vitamin C, which causes oxidative stress via GSH depletion." (PMID 30456204, 2018). "Several studies indicated that different mutation types of KRAS, NRAS, and BRAF gene in colorectal cancer tissues have different biological characteristics and lead to different biological changes, which may have different effects on patients." (PMID 30416987, 2018).